FAAH (fatty acid amide hydrolase)
Diseases named in the same sentence as FAAH in open-access papers (continued):
Sharing a sentence is not in itself a finding about the gene and the disease.
diabetes (4 papers, 2012 to 2023). "Furthermore, the homozygous T/T genotype of FAAH rs2295632 has been statistically associated with type 2 diabetes mellitus." (PMID 37509416, 2023). "We show that whole body FAAH deletion in mice mimics several metabolic aspects of pre-diabetes including impaired fuel utilization, hyperinsulinemia, and hepatic, skeletal muscle and adipose tissue insulin resistance." (PMID 22442717, 2012). "The current study shows that inhibition of FAAH may present as a new therapeutic approach to the treatment of dysfunctional intestinal motility in diabetes." (PMID 35878381, 2022). "However, in obese humans, FAAH or MGL activity in adipocytes is not affected by diabetes, dyslipidaemia or other markers of metabolic dysfunction." (PMID 24593280, 2014). "Therefore, the finding that FAAH activity was reduced in the ZDF rat and not diabetic humans might be ascribed to the fact that diabetes is uncontrolled in the ZDF, and this idea should be further pursued." (PMID 24593280, 2014).
diabetic neuropathy (4 papers, 2017 to 2025). A chronic, pathological complication associated with diabetes mellitus, where nerve damages are incurred due to diabetic microvascular injury involving small blood vessels that supply these nerves, resulting in peripheral and/or autonomic nerve dysfunction. "In the rostroventromedial medulla (RVM) area of the brain of rats with diabetic neuropathy FAAH protein levels were increased." (PMID 28373843, 2017). "Another FAAH inhibitor, ASP8477, was used in a clinical trial of painful diabetic neuropathy, but it did not produce sufficient anti-nociceptive effects." (PMID 32093166, 2020).
eating disorder (4 papers, 2010 to 2026). A broad group of psychological disorders with abnormal eating behaviors leading to physiological effects from overeating or insufficient food intake. "Although the sample size in this study is larger than in any other prior study of the genetic association of the FAAH c.385C>A SNP with eating disorders, the results should be confirmed by independent studies." (PMID 25077173, 2014).
memory impairment (4 papers, 2018 to 2023). "First, we evaluated the influence of an acute administration of FAAH and MAGL inhibitors on the long-term memory acquisition, and then we assessed the impact of these inhibitors on the memory impairment provoked by an acute injection of MK-801." (PMID 31004320, 2019). "However, the memory impairments by indirect activation of CB1 receptor (i.e., via FAAH and MAGL) inhibition often depend on dose." (PMID 29695817, 2018).
mood disorder (4 papers, 2015 to 2025). A cognitive disorder a disturbance in which the person's mood is hypothesized to be the main underlying feature. "The FAAH, part of the endocannabinoid system, also contributes to mood regulation and susceptibility to mood disorders and suicidal behavior." (PMID 39940809, 2025). "ECS is a homeostatic system; therefore it is safe to suggest that CB1R and FAAH downregulation in the mPFC leads to dysregulated endocannabinoid signalling in this brain area and a consequentially higher risk for the development of mood disorders and psychiatric diseases." (PMID 39503008, 2024).
neuroblastoma (4 papers, 2011 to 2024). Neuroblastoma (NB) is the most common solid, extracranial childhood tumor. "Research in human neuroblastoma cells first identified estrogen and glucocorticoid response elements (EREs and GREs, respectively) in the FAAH promoter that regulated transcriptional activity independent of their ligand." (PMID 38184644, 2024). "URB597, another FAAH inhibitor, was shown to reduce proliferation of neuroblastoma cells when combined with the FAAH substrate AEA." (PMID 31143113, 2019). "Recently, by describing an inhibitory effect of the fatty acid amide hydrolase (FAAH) inhibitor methyl arachidonyl fluorophosphates (MAFP) on the AEA uptake of neuroblastoma and astrocytoma cells, the importance of FAAH activity for AEA uptake was demonstrated." (PMID 25395667, 2014). "In vitro, leptin has been shown to increase FAAH activity in T lymphocytes, although not in neuroblastoma cells, and our results suggest that in vivo leptin does not significantly affect FAAH activity in adipocytes." (PMID 21813022, 2011).
neuropathy (4 papers, 2019 to 2024). A disorder affecting the nervous system that manifests with pain, tingling, numbness, and/or muscle weakness. "Other agents deemed to be effective in HIV neuropathy, as per the authors’ perspectives and clinical data, are FAAH (fatty acid amide hydrolase) inhibitors and IPM (indomethacin plus minocycline) regimens." (PMID 38397910, 2024).
ovarian carcinoma (4 papers, 2020 to 2024). A malignant neoplasm originating from the surface ovarian epithelium. "Bagavandoss and colleagues demonstrated CB1 and FAAH expression in ovarian surface epithelium, the site from which some ovarian cancers often arise, providing another clue for a possible involvement of the ECS in ovarian cancer." (PMID 33375539, 2020). "Therefore, the combination of CB2 agonist with FAAH and/or MAGL inhibitors with light irradiation could potentially and significantly reduce the aggressiveness of breast and/or ovarian cancer." (PMID 35242036, 2022). "Interestingly, our findings suggest that chronic administration of CB2 agonist should most likely be combined with FAAH and/or MAGL inhibitors to prevent the generation of a pool of free fatty acid leading to increase in tumor growth and endocannabinoid (AEA, 2-AG) levels in ovarian cancer." (PMID 35242036, 2022).
secondary hypertension (4 papers, 2018 to 2023). High blood pressure caused by an underlying medical condition. "Nevertheless, in previous studies we have reported that chronic FAAH inhibition in a model of secondary hypertension considerably elevated intramyocardial lipid and glycogen deposition along with palmitic acid uptake in order to facilitate adjustment in fuel demands of overloaded left ventricle." (PMID 32326330, 2020). "In previous studies, we found that the FAAH inhibitor URB597 exerted a pro-oxidative effect on the heart, liver, kidneys, and blood plasma of rats with primary and secondary hypertension." (PMID 32664225, 2020). "In our recent study, in which BP was determined with the tail-cuff method only, a 2-week administration of the FAAH inhibitor URB597 did not affect BP and HR in SHR, but reduced BP in the deoxycorticosterone acetate (DOCA)-salt model of secondary hypertension." (PMID 37446125, 2023).
Tourette syndrome (4 papers, 2015 to 2022). A neurologic disorder caused by defective metabolism of the neurotransmitters in the brain. "Among the following strategies, we find the use of FAAH inhibitors, for instance, using the compound PF-04457845 in Tourette syndrome (NCT02134080) or cannabis use disorder (NCT03386487)." (PMID 35492718, 2022). "A search of ClinicalTrials.gov identified a number of registered ongoing trials of FAAH inhibitors for substance use disorders, Tourette Syndrome, and pain." (PMID 34959715, 2021). "However, this inhibitor is currently under clinical investigation for treatment of cannabis withdrawal, PTSD, and Tourette syndrome (International Clinical Trials Registry Platform), the results from which will provide important clinical data on the effect of FAAH inhibition on affective responding." (PMID 26342110, 2015).
amyloid (3 papers, 2021 to 2025). "Specific to AD, FAAH inhibitors have demonstrated protective effects against amyloidosis, resulting in improved cognitive function, improved memory, lower oxidative stress, and lower neuroinflammation in an AD mouse model." (PMID 40332352, 2025). "To assess the potential beneficial effect induced by FAAH inhibition on amyloid plaque accumulation, we analyzed both the number and area of plaques by using the Congo Red procedure." (PMID 39596118, 2024). "What is the causal link between FAAH deletion and TREM2 overexpression in the presence of amyloid pathology?" (PMID 34587978, 2021). "We did not observe the downregulation of homeostatic genes in AD groups, and while TREM2, CLEC7A and CTSD were indeed overexpressed in the presence of amyloidosis, only TREM2 and CTSD upregulation seemed to be specific of FAAH deletion in pathological conditions." (PMID 34587978, 2021).
cognitive decline (3 papers, 2018 to 2024). "Therefore, in the current study, we examined whether the pharmacological or genetic inhibition of FAAH would increase sleep and rescue cognitive decline in PS19 mice." (PMID 38543105, 2024). "Therefore, to test the hypothesis that FAAH KO would protect against cognitive decline in PS19 animals, we conducted the Morris water maze (MWM) test of spatial learning and contextual/acoustic cue fear conditioning to investigate hippocampal-dependent learning and memory." (PMID 38543105, 2024). "FAAH and MAGL inhibitors possess several neuroprotective effects and are therefore considered promising molecules in the prevention of cognitive decline and AD pathogenesis." (PMID 37700370, 2023). "We report that FAAH KO was not able to protect PS19 mice from progressive sleep loss and hyperarousal, neuroinflammation, or cognitive decline." (PMID 38543105, 2024). "Counter to our expectations, FAAH knockout did not protect PS19 mice from progressive sleep loss, neuroinflammation, or cognitive decline." (PMID 38543105, 2024). "Treatment with the fatty acid amide hydrolase (FAAH) inhibitor URB597, might regulate autophagy, suppress apoptosis, and ameliorate ultrastructural neurodegeneration and cognitive decline in the CA1 area via the m-TOR pathway." (PMID 29904335, 2018). "In order to examine the suitability of the chronic loss of FAAH activity as a possible therapeutic approach, we examined whether the complete genetic knockout (KO) of FAAH would protect PS19 mice from progressive hyperarousal, neuroinflammation, and cognitive decline." (PMID 38543105, 2024). "However, FAAH KO in PS19 mice did not rescue hyperarousal, neuroinflammation, or cognitive decline." (PMID 38543105, 2024).
colorectal cancer (3 papers, 2017 to 2023). A primary or metastatic malignant neoplasm that affects the colon or rectum. "We also examined the levels of FAAH in other common solid tumours, such as lung, breast, and colorectal cancer, and found that the expression of FAAH was specific in GC." (PMID 36702852, 2023). "AEA-mediated death in HT29 colorectal cancer cells was enhanced by its co-administration with the FAAH inhibitor, MAFP." (PMID 29066974, 2017). "However, AA catalysed by FAAH was found to be highly expressed in the tissues of patients with colorectal cancer metastasis." (PMID 36702852, 2023). "Several nonselective and selective inhibitors of FAAH, including URB597, a relatively selective, irreversible, carbamate-based inhibitor, exert potential anticancer effects in ovarian, breast, prostate, and colorectal cancers, suggesting that targeting FAAH might be a promising anticancer strategy." (PMID 37024452, 2023). "In addition, AEA levels and FAAH expression and activity were elevated in human colorectal cancer tissue compared to non-tumor colon tissue." (PMID 29066974, 2017).
endometrial carcinoma (3 papers, 2019 to 2022). A malignant tumor arising from the epithelium that lines the cavity of the uterine body. "It is also reported that FAAH expression level in endometrial cancer cell contributes to the regulation of plasma anandamide and N- palmitoylethanolamide concentrations in postmenopausal women suffering from endometrial cancer." (PMID 35190739, 2022). "FAAH and NAPE-PLD have been shown to be expressed in endometrial carcinoma and Ishikawa cells." (PMID 35128447, 2021). "Unlike the transcript levels for FAAH, these were not significantly different in any of the endometrial cancer types or grades when compared to control atrophic tissues." (PMID 31921630, 2019). "Although our data show that peripheral lymphocytic FAAH activities are however decreased in endometrial cancer compared to the atrophic controls, this reduction failed to reach statistical significance, probably due to the small number of samples studied." (PMID 31921630, 2019).
gastric cancer (3 papers, 2023 to 2025). A primary or metastatic malignant neoplasm involving the stomach. "Promoter hypomethylation of C1orf35 and FAAH in early-stage gastric cancer underscores their potential as biomarkers for accurate diagnosis and treatment." (PMID 39575189, 2024). "Central genes like C1orf35 and FAAH have demonstrated both predictive and prognostic significance as biomarkers based on methylation, setting the stage for accurate diagnosis and targeted treatment of gastric cancer." (PMID 39575189, 2024). "Notably, the hypomethylation of the three CpG islands in C1orf35 and the single CpG island in FAAH was significantly different in stage I/II gastric cancer patients compared to normal tissues." (PMID 39575189, 2024).
glaucoma (3 papers, 2020 to 2025). Increased pressure in the eyeball due to obstruction of the outflow of aqueous humor. "FAAH, known for hydrolyzing fatty acid amides, has been implicated for regulating endocannabinoid signaling within the eye and modulating intraocular pressure, making it a target for glaucoma therapies." (PMID 40505410, 2025). "In this context, the fatty acid amide hydrolase inhibitors and endocannabinoid system were investigated as glaucoma neuroprotectans." (PMID 32967086, 2020).
Infertility (3 papers, 2012 to 2026). "The biosynthesis of AEA through NAPE-PLD and, to a lesser extent, its degradation by FAAH, were both significantly impaired in infertile versus fertile sperm, leading to a significant reduction of AEA content in seminal plasma of infertile sperm." (PMID 23082196, 2012). "Interestingly, NAPE-PLD and FAAH activities were significantly decreased in sperm from infertile versus fertile men." (PMID 23082196, 2012). "In particular, in infertile sperm NAPE-PLD and FAAH were reduced respectively compared with ∼25% and ∼50% of the values in fertile sperm." (PMID 23082196, 2012). "Furthermore, we highlight the potential implications of altered FAAH activity in ovarian disorders such as polycystic ovary syndrome (PCOS), premature ovarian insufficiency (POI), and infertility." (PMID 41683532, 2026). "Interestingly, the ratio between FAAH and NAPE-PLD activity (from ∼19 to ∼40) and that between MAGL and DAGL activity (from ∼2.5 to ∼5.0) almost doubled in infertile versus fertile sperm." (PMID 23082196, 2012).
Insulin resistance (3 papers, 2012 to 2019). Increased resistance towards insulin, that is, diminished effectiveness of insulin in reducing blood glucose levels. "FAAH deficiency also promotes insulin resistance and liver steatogenesis, two key steps in the pathogenesis of non-alcoholic fatty liver disease, and CB1 antagonists have been proposed in the management of NASH." (PMID 22442717, 2012). "FAAH−/− mice are hyperinsulinemic and have adipose, skeletal and hepatic insulin resistance as indicated by stable isotope phenotyping (SIPHEN)." (PMID 22442717, 2012). "The unsuppressed HGP from glycerol, despite basal hyperinsulinemia, seen in FAAH−/− mice suggested hepatic insulin resistance." (PMID 22442717, 2012). "Stable isotope flux phenotyping revealed that FAAH−/− mice displayed hepatic, skeletal and adipose insulin resistance." (PMID 22442717, 2012). "We hypothesize that the hepatic insulin resistance (unsuppressed glucose production and impaired fuel switching) seen in the pre-diabetic FAAH−/− mouse can be attributed, in part, to its dysregulated lysine acetylation." (PMID 22442717, 2012).
primary hypertension (3 papers, 2020 to 2021). "The present study tested whether chronic administration of the fatty acid amide hydrolase (FAAH) inhibitor [3-(3-carbamoylphenyl) phenyl]N-cyclohexylcarbamate (URB597) to rats with primary hypertension (SHR) can modify redox balance and consequently brain phospholipid metabolism." (PMID 32664225, 2020). "All designed experiments were conducted on the animal model of primary hypertension, i.e., spontaneously hypertensive rat (SHR) with chronic ECS activation by injections of fatty acid amide hydrolase (FAAH) inhibitor—URB597." (PMID 32326330, 2020). "For this purpose, we used the most common animal model of primary hypertension, SHR, which responds to almost all classes of the approved antihypertensive drugs, and normotensive controls, WKY, which were chronically treated with the FAAH inhibitor URB597 (1 mg/kg/12 h for 2 weeks)." (PMID 34063297, 2021). "Moreover, we observed that 2-week URB597 treatment caused a substantial reduction in cardiac DAG pool in the model of primary hypertension compared to the hypertensive group not treated with FAAH inhibitor (–21.8%, P < 0.05)." (PMID 32326330, 2020).
psoriasis (3 papers, 2018 to 2020). An autoimmune condition characterized by red, well-delineated plaques with silvery scales that are usually on the extensor surfaces and scalp. "Elevated levels of the two major endocannabinoids (anandamide and 2-arachidonoyl glycerol) have been observed in patients with both forms of psoriasis, despite the increased activity of enzymes degrading these endocannabinoids (e.g., fatty acid amide hydrolase and monoacylglycerol lipase)." (PMID 33266237, 2020). "Therefore, elevated levels of two main endocannabinoids anandamide (AEA) and 2-arachidonoylglycerol (2-AG) were observed in patients with both forms of psoriasis despite elevated activity of enzymes degrading these endocannabinoids (FAAH and MAGL)." (PMID 30301214, 2018). "The levels of FAAH and MAGL tend to increase in psoriasis and after the UV irradiation of keratinocytes, as demonstrated by our findings." (PMID 32121131, 2020). "Our results confirm the lack of CBD effect on FAAH/MAGL activity in the keratinocytes of healthy people and patients with psoriasis but show a decrease in their activity after UV irradiation." (PMID 32121131, 2020).
rheumatoid arthritis (3 papers, 2008 to 2025). A chronic, systemic autoimmune disorder characterized by inflammation in the synovial membranes and articular surfaces. "In patients with rheumatoid arthritis, N-acylethanolamine anandamide (AEA), a dual inhibitor of fatty acid amide hydrolase/cyclooxygenase-2 (FAAH/COX-2), demonstrated the ability to inhibit MAPK signaling." (PMID 39022308, 2024).
allergic asthma (2 papers, 2017 to 2025). A asthma with a basis in a pathological type I hypersensitivity reaction. "In an allergic asthma model, guinea pigs were challenged with ovalbumin and treated with both FAAH and MAGL inhibitors to assess airway inflammation and hyperreactivity." (PMID 40244178, 2025). "Whether palmitic amide (L8) combined with the fatty acid amide hydrolase enzyme and degraded in the formation of allergic asthma needs to be further investigated." (PMID 28287417, 2017). "However, the selective inhibition of MAGL (JZL184) and dual inhibition of FAAH and MAGL (JZL195) alleviated both the inflammatory response and AHR, suggesting a promising therapeutic strategy for allergic asthma." (PMID 40244178, 2025).
anorexia nervosa (2 papers, 2008 to 2014). A disorder most often seen in adolescent females characterized by a refusal to maintain a minimally normal body weight, an intense fear of gaining weight, a disturbance in body image, and, in postmenarcheal females, the development of amenorrhea. "The functional c.385C>A single-nucleotide polymorphism (SNP) in the fatty acid amide hydrolase (FAAH) gene, one of the major degrading enzymes of endocannabinoids, is reportedly associated with anorexia nervosa (AN)." (PMID 25077173, 2014). "The aim of this study was to analyse whether nucleotide sequence variations in the CNR1, FAAH, NAAA and MGLL genes are associated with anorexia nervosa (AN)." (PMID 19014633, 2008).